IFI6 (interferon alpha inducible protein 6)
Diseases named in the same sentence as IFI6 in open-access papers (continued):
Sharing a sentence is not in itself a finding about the gene and the disease.
COVID-19 (continued). "Among prominent ones are CXCL10, a marker of acute viral infection, ISG15, both an extracellular cytokine and an intracellular protein modifier, IFI6 that may be involved in the regulation of cell apoptosis and IFI27, a proven predictor for COVID-19 outcomes." (PMID 37685932, 2023). "Of note, we observed a localized downregulation of certain complement factors (C1QB, CFD, and C7) and interferon response genes (IFI6 and ISG15), in contrast to their enrichment in COVID-19 lungs compared to control lungs in our samples and in others analyzed in previous works." (PMID 37858234, 2023). "In this study, the relative expression of IRF9, CCL5, IFI6, TGFB1, IL1B, OAS1, and TFRC genes (related to immunity and antiviral activity) was analyzed in upper airway samples from 127 individuals (97 COVID-19 positive and 30 controls) by using a two-step RT-PCR." (PMID 37389217, 2023). "Genes enriched in male Mo/DCs relative to female Mo/DCs included multiple ISGs (IFI27, IFI6, and ISG15), prompting us to perform an upstream regulator analysis to identify cytokines predicted to promote sex-biased Mo/DC gene expression patterns in patients with COVID-19." (PMID 37606044, 2023). "COVID-19 neutrophils preferentially transitioned from the apex of the trajectory, which was an immature state (TOP2A-expressing) to an IFNactive state characterized by IFITM1, IFITM2 and IFI6 expression (clusters 1–4 and 5; Online Atlas) and activation of type I IFN signaling pathways." (PMID 34782790, 2022). "We therefore measured the expression of IFI6 and GBP5 (relative to the reference gene RPP30) using qPCR assays on swabs from a new cohort of patients with (n = 72) or without (n = 72) COVID-19 (Data Set S3)." (PMID 36507688, 2023). "IFI6, ISG15, IFI27, and IFI35 were increased in mild, and decreased or not changed in severe COVID-19, compared to healthy controls." (PMID 34108966, 2021).
breast carcinoma (29 papers, 2015 to 2025). "Our findings revealed that IFI6 was upregulated in breast cancer and was associated with histological subtypes and lymph node metastasis status." (PMID 41107386, 2025). "ST_7 showed higher gene expression of interferon (IFN)‐inducible genes such as ISG15, IFIT1 and IFI6, which were recently demonstrated to be associated with ER+ breast cancer therapy resistance." (PMID 38282415, 2024). "In conclusion, IFI6 serves as a potential biomarker for immune infiltration and poor prognosis in breast cancer and may offer novel insights into risk stratification and immunotherapeutic strategies." (PMID 41107386, 2025). "The poor metastasis-free survival in breast cancer patients was linked to upregulation of mitochondrial antiapoptotic protein IFI6 that might be involved in regulation of mitochondrial ROS production." (PMID 36497286, 2022). "We found that the loss of IFI6 expression resulted in dysregulated DNA replication, as indicated by the detection of significantly fewer ongoing DNA replication forks and more stalled forks in IFI6 shRNA expressing breast cancer cells than in NS shRNA expressing cells." (PMID 36338541, 2022). "To address this, we employed bioinformatics analyses to investigate the expression and prognostic significance of IFI6 in breast cancer." (PMID 41107386, 2025). "IFI6 is considered as a pro-survival gene because of its high expressed in psoriasis, breast cancer, colorectal cancer, and gastric cancer." (PMID 40100809, 2025). "Kaplan-Meier plotter analysis demonstrated that high IFI6 expression correlated with poor prognosis in breast cancer patients with ER-positive, PR-positive, HER2-positive, and lymph node-positive subtypes." (PMID 41107386, 2025). "Overexpression of IFI6 in breast cancer cells inhibits apoptosis by inhibiting the tumour-suppressing IFN-1 characteristics, activating immune-endocrine-elicited redox signalling." (PMID 39070493, 2024). "Interferon-α-inducible protein 6 (IFI6) has been extensively studied across various cancer types, such as lung adenocarcinoma, myeloma, gastric cancer, pancreatic cancer, breast cancer, prostate cancer, and ovarian cancer." (PMID 38473938, 2024). "In breast cancer, upregulation of IFI6 in endosomes and mitochondria and the binding IFI6 with RAB+ endosomes dysregulate the mitochondrial resistance to apoptosis and thus ensued anti-apoptosis in cancer cells." (PMID 39070493, 2024). "Consistently, UBE2T inhibition downregulated IFI6 expression, promoting DNA replication stress, cell cycle arrest, and apoptosis and suppressing breast cancer cell growth." (PMID 36338541, 2022). "After IFI6 knockdown was validated, these breast cancer cell lines were tested for their abilities to grow in an anchorage-independent manner using soft-agar assays." (PMID 36338541, 2022). "Collectively, these studies identify UBE2T as a facilitator of breast cancer tumor growth through the suppression of IFI6 expression, DNA replication stress, and apoptosis induction." (PMID 36338541, 2022). "RNA sequencing analysis identified interferon alpha–inducible protein 6 (IFI6) as a key downstream mediator of UBE2T function in breast cancer cells." (PMID 36338541, 2022). "We found that IFI6 knockdown in breast cancer cells resulted in significant reductions in the abilities of these cells to form colonies in soft agar, mimicking the growth inhibitory phenotype observed in UBE2T-knockdown cells." (PMID 36338541, 2022). "We identified that UBE2T regulates DNA replication stress in breast cancer cells by stimulating the expression of IFI6, suppressing DNA replication stress, cell cycle arrest, and apoptosis induction." (PMID 36338541, 2022). "We also found that IFI6 was one of the most significantly expressed genes next to UBE2T in breast cancer cell lines." (PMID 36338541, 2022). "Based on these results, we next investigated the role of UBE2T-regulated IFI6 expression in breast cancer cell growth." (PMID 36338541, 2022).
breast carcinoma (continued). "Mechanistically, UBE2T inhibition in breast cancer cells suppresses interferon alpha–inducible protein 6 (IFI6) expression, resulting in DNA replication stress, cell cycle arrest, and apoptosis induction." (PMID 36338541, 2022). "Very interestingly, in breast cancer, IFI6 was revealed to promote the metastatic potential of breast cancer cells through mtROS." (PMID 34055036, 2021). "Especially, IFI6 was recently reported to promote metastatic potential of breast cancer cells through mitochondrial ROS (mtROS)." (PMID 33539340, 2021). "The anti-apoptotic activity of IFI6 has been observed in breast cancer cells, gastric cancer cells, vascular endothelial cells, and human myeloma cells." (PMID 34490145, 2021). "Six hub genes, including IFIT1, ISG15, IFI6, GOLM5, KLHL35, and OAS2, were associated with the total survival probability in breast cancer patients." (PMID 30646630, 2019). "In breast cancer, upregulation of mitochondrial antiapoptotic protein G1P3 (IFI6) was associated with poor distance metastasis-free survival (DMFS)." (PMID 29899394, 2018). "For the last decade, IFI6 was generally regarded as a pro-survival gene since it is expressed at high levels in gastric cancer, colorectal cancer, breast cancer, myeloma, tongue squamous cell carcinoma, and in psoriasis." (PMID 26244642, 2015). "AL445490.1, the lncRNA with the highest prediction score for IFN-α (mean score = 0.931), is antisense and positioned intronic and upstream of IFN-α–inducible protein 6 (IFI6) and was previously found to be highly expressed in an inflammatory subtype of breast cancer." (PMID 38131377, 2023). "We ectopically expressed IFI6 in breast cancer cells expressing UBE2T shRNA and tested whether IFI6 overexpression restored normal DNA replication by preventing DNA replication stress and apoptosis." (PMID 36338541, 2022). "Based on these results, we performed experiments to determine whether IFI6 acts as a downstream mediator of UBE2T-induced tumor growth in breast cancer." (PMID 36338541, 2022). "Based on these findings, we examined whether IFI6 knockdown resulted in DNA replication stress in breast cancer cells, leading to growth inhibition." (PMID 36338541, 2022). "Similarly, IFI6 protein expression assessed by IHC using a breast cancer TMA (#BC081120f) demonstrated the significant elevation of IFI6 expression in a large majority of patient-derived breast cancer samples compared with normal breast tissue samples." (PMID 36338541, 2022). "To explore whether IFI6 plays a role in breast cancer cell growth downstream of UBE2T, we first examined whether IFI6 is overexpressed in patient-derived breast cancer samples compared with normal breast tissues, similar to UBE2T overexpression." (PMID 36338541, 2022). "In this study, we showed that the inhibition of UBE2T expression correlated with the repression of IFI6 expression, the activation of the DNA replication stress pathway, G1 cell cycle arrest, and apoptosis induction, leading to the inhibition of breast cancer cell growth and proliferation." (PMID 36338541, 2022). "Breast cancer cells with IFI6 inhibition displayed similar phenotypes as those with UBE2T inhibition, and ectopic IFI6 expression in UBE2T-knockdown breast cancer cells prevented DNA replication stress and apoptosis and partly restored breast cancer cell growth." (PMID 36338541, 2022). "IFI6, also known as GIP3, which belongs to the ISG12 gene family, has been reported as a mitochondrial and apoptotic protein in myeloma, gastric, and breast cancer, and therefore IFI6-induced mitochondrial redox deregulation bestows metastatic potentials in these cancers." (PMID 34439992, 2021). "Indeed, IFI6 has a direct role in the formation of migration structures in breast cancer metastasis." (PMID 34082779, 2021).
breast carcinoma (continued). "It has been shown that IFI6 plays anti-apoptosis roles in gastric and breast cancer cells, human myeloma cells and vascular endothelia cells, mainly through stabilizing mitochondrial membrane potential, inhibiting activation of caspase 3 and caspase 9, and decreasing Bax/Bcl-2." (PMID 34399768, 2021). "Besides, it has been reported that IFI6-induced mitochondrial redox deregulation facilitates breast cancer metastasis." (PMID 34399768, 2021). "Furthermore, IFI6 was suggested to facilitate breast cancer metastasis by modulating mitochondrial ROS production." (PMID 32727517, 2020). "The expression of IFI27 and IFI6 is upregulated in epithelial malignancies, breast cancer, and ovarian cancer, and their expression may be abundant in cancer cells." (PMID 27629773, 2016). "In addition, IFI6 is regarded as a crucial predictor of poor outcome in breast cancer." (PMID 37670388, 2023). "Although, in our study we find that UBE2T mediates its function through IFI6 in UBE2T-IFI6-DNA replication-apoptosis pathway dependent manner in breast cancer cells, it is possible that IFI6 could influence cell growth and other phenotypes by alternative UBE2T-independent mechanisms." (PMID 36338541, 2022). "IFI6, also known as G1P3, is a mitochondrial localized antiapoptotic protein that has been shown to promote the metastatic ability of breast cancer cells through mtROS." (PMID 36568384, 2022). "We further showed that IFI6 overexpression effectively reverses DNA replication stress and the inhibition of colony-forming growth induced by UBE2T knockdown in breast cancer cells, partially restoring breast cancer cell proliferation." (PMID 36338541, 2022). "We analyzed publicly available breast cancer datasets and found that, similar to UBE2T mRNA, IFI6 mRNA was significantly overexpressed in breast cancer samples relative to normal breast samples." (PMID 36338541, 2022). "Meanwhile, we found that CEP55, HIST1H2BO, IFI6, KIAA0101, PBK, SPAG5, and SPP1 were significantly upregulated in breast cancer compared to normal samples." (PMID 34055036, 2021). "In 1104 breast cancer tissues (StarBase database), the positive correlation between IRF1 and IFI6 mRNA levels was supported by Spearman correlation analysis." (PMID 34399768, 2021). "Interferon alpha-inducible protein 6 (IFI6), also known as G1P3 has been shown to contribute to hyperplasia, tamoxifen resistance and poor outcomes in breast cancer." (PMID 35096006, 2021). "However, the ectopic expression of IFI6 in UBE2T-knockdown cells prevented DNA replication stress and apoptosis and partly restored breast cancer cell growth." (PMID 36338541, 2022). "Type I IFNs also upregulate the survival factors MCL1, the apoptosis regulator BCL2 family member (MCL1) and interferon alpha inducible protein 6 (IFI6, best known as G1P3) in myeloma and estrogen-receptor positive breast cancer, respectively, thus promoting poor patient outcome." (PMID 34571733, 2021). "Although the role of IFI6 in slowing the growth of MT3 expressing breast cancers is not known, the fact that it is overexpressed will provide a starting point to define the mechanism underlying MT3’s ability to inhibit the growth of MCF-7 cells." (PMID 28545470, 2017). "However, we would also like to note that it is also possible that IFI6 may also influence cell growth and other tumor phenotypes by regulating alternative UBE2T-independent pathways to promote breast cancer cell growth." (PMID 36338541, 2022).
psoriasis (14 papers, 2013 to 2025). An autoimmune condition characterized by red, well-delineated plaques with silvery scales that are usually on the extensor surfaces and scalp. "In our large cohort, expression of IFI6 in psoriasis lesions was up-regulated nearly 5-fold, although prior work using RT-PCR and epidermal fractions have estimated 400-fold elevation of IFI6 in lesional skin." (PMID 24260178, 2013). "Meanwhile, bioinformatic analysis of psoriasis and SLE cases suggested IFI6 is a primary IFN-inducible gene." (PMID 35609018, 2022). "IFI6 was highly expressed in SLE, psoriasis, and type I diabetes and was also able to forecast the treatment response of rheumatoid arthritis patients to tocilizumab." (PMID 35711463, 2022).
gastric cancer (12 papers, 2015 to 2025). A primary or metastatic malignant neoplasm involving the stomach. "The IFITM family may also be mutated in gastric cancer, regulating the entry of viruses into host cells, activating IFI6 and FKBP10 and leading to TF phosphorylation like STAT1." (PMID 39228892, 2024). "In addition, the expression of IRF1 and IFI6 are is associated with drug sensitivity in gastric cancer." (PMID 34082779, 2021). "Recent findings have verified that a mitochondrial inner membrane protein, interferon alpha inducible protein 6 (IFI6), is involved in various malignancies, including esophageal squamous cell carcinoma, myeloma, breast and gastric cancers." (PMID 34399768, 2021). "In gastric cancer, elevated alpha-inducible protein 6 (IFI6) and FKBP prolyl isomerase 10 (FKBP10) could be responsible for the activation of STAT1 expression, diminishing antiviral responses." (PMID 39228892, 2024). "In addition, both IRF1 and IFI6 are positively correlated with the drug-specific chemical sensitivity of gastric cancer." (PMID 34082779, 2021). "Recent findings demonstrated that interferon alpha inducible protein 6 (IFI6), an interferon (IFN)-stimulated gene (ISG), is enriched mainly in the inner mitochondrial membrane and implicated in diverse malignant diseases, including myeloma and breast and gastric cancers." (PMID 32727517, 2020). "PAH and gastric cancer have two (CDC25B, and IFI6) common overregulated genes located in the nucleoplasm, along with fifteen TFs, the transmembrane helix, and the endoplasmic reticulum membrane, related to negative regulation of the apoptotic process." (PMID 39791702, 2024).
myeloma (10 papers, 2008 to 2023). "In the study of hematological tumors, aberrantly expressed IFI6 in multiple myeloma is an important factor leading to the chemoresistance of myeloma cells." (PMID 37670388, 2023).
melanoma (8 papers, 2016 to 2024). A malignant, usually aggressive tumor composed of atypical, neoplastic melanocytes. "IFI6 has also been shown to mediate mutated N-Ras-induced transformation and melanoma growth, and the knockdown of IFI6 resulted in DNA replication stress due to dysregulated DNA replication via E2F2, resulting in senescence or apoptosis." (PMID 37686559, 2023). "We did not observe similar changes in mRNA levels of E2F2 or its target genes after IFI6 knockdown in BRAF-mutant or NF1-deficient melanoma cell lines." (PMID 27608486, 2016). "In melanoma cells and primary human melanocytes, IFI6 loss results in the induction of cellular senescence as a result of E2F2-mediated dysregulated DNA replication and consequent DNA damage." (PMID 27608486, 2016). "Additionally, IFI6 overexpression significantly correlated with the NRAS mutation status in patient-derived melanoma samples." (PMID 27608486, 2016). "Because IFI6 is upregulated in NRAS-mutant melanoma, and its expression correlates with NRAS mutation status, this subgroup of melanoma could be targeted using this therapeutic approach." (PMID 27608486, 2016). "Our previous study in melanoma cells showed that IFI6 regulates DNA replication stress pathways to promote melanoma growth." (PMID 36338541, 2022). "We also evaluated senescence markers in this scenario and found that simultaneous knockdown of E2F2 and IFI6 prevented IFI6-induced senescence in melanoma cells." (PMID 27608486, 2016). "NRAS-mutant melanoma were significantly more resistant to the cytotoxic effects of DNA replication stress-inducing drugs, and knockdown of IFI6 increased sensitivity to these drugs." (PMID 27608486, 2016). "Next, we asked if the E2F2 upregulation that results from IFI6 knockdown is necessary for melanoma growth inhibition." (PMID 27608486, 2016). "Toward this end, we knocked down the expression of IFI6 in three NRAS-mutant melanoma cell lines (YUGASP, M318, and SKMEL-103) and one NRAS wild-type melanoma cell line (YUVON) and monitored their colony- and tumor-forming ability." (PMID 27608486, 2016). "Our results show that shRNA-induced knockdown of IFI6 inhibited the ability of NRASQ61K mutant melanoma cells to form colonies in soft agar and to form tumors in mice." (PMID 27608486, 2016). "To answer this question, we knocked down the expression of IFI6 in the NRAS-mutant melanoma cell line YUGASP and performed a microarray analysis." (PMID 27608486, 2016). "Knockdown of IFI6 increased the sensitivity of NRAS-mutant melanoma to DNA replication stress-inducing agents, and simultaneous loss of E2F2 and IFI6 rescues this effect." (PMID 27608486, 2016). "After confirming the role of IFI6 in the regulation of melanocyte transformation and melanoma growth, we asked how IFI6 regulates these phenotypes." (PMID 27608486, 2016). "To test this, we knocked down IFI6 in NRAS-mutant melanoma cell lines, YUGASP, M318, and SKMEL-103, and measured well-accepted markers of cellular senescence including senescence-associated β-gal (SA-β-gal) and acetylated histone H3K9 (H3K9Ac)." (PMID 27608486, 2016). "Based on these findings, we hypothesized that the loss of IFI6 results in dysregulated DNA replication via E2F2 upregulation, which in turn blocks NRAS-mutant melanoma tumor growth and melanomagenesis." (PMID 27608486, 2016). "Furthermore, an analysis of previously published melanoma datasets revealed that IFI6 is overexpressed in melanoma samples." (PMID 27608486, 2016). "Based on these results, we asked if IFI6 is necessary for NRAS-mutant melanoma-driven tumor growth." (PMID 27608486, 2016). "Furthermore, simultaneous knockdown of E2F2 and IFI6 in melanoma cells resulted in a lower percentage of cells in S phase and normalized DNA replication compared with cells expressing IFI6 shRNA." (PMID 27608486, 2016).